EGF (epidermal growth factor)
Diseases named in the same sentence as EGF in open-access papers (continued):
Sharing a sentence is not in itself a finding about the gene and the disease.
cancer (continued). "Thus, we can cultivate even some extremely slow-growing spheroids by supplementing the basal cancer medium with three additional ingredients, EGF, bFGF, and NECA." (PMID 29774115, 2018). "AQP3 has been suggested to increase EGF-induced cancer growth and migration by mediating H2O2 flux." (PMID 29922644, 2018). "HuR plays an important role in cancer cell proliferation by increasing the levels of proliferation related regulators (including cyclins, epidermal growth factor, c-Myc, eukaryotic translation initiation factor and others) and regulating several anti-apoptotic factors and signaling pathways." (PMID 29728635, 2018). "For example, M2 macrophages secrete EGF, which promotes cancer cell progression." (PMID 29580202, 2018). "Notably, AMPK knockdown in cancer cells attenuated EGF-induced glucose uptake and lactate production." (PMID 30413706, 2018). "Additionally, many of the identified Hb target genes are involved in the epidermal growth factor (EGF) pathway that has various roles in development and cancer including cell division, differentiation, cell survival and migration." (PMID 29360820, 2018). "EGF significantly induced STAT3 phosphorylation and elevated the mRNA levels of LGR5 in the HT29 cells, implying that addition of EGF activated STAT3 in the cancer stem-like tumorspheres, thus contributing to the formation and survival of EGFR-positive CRC stem-like tumorspheres." (PMID 30068339, 2018). "We then determined whether activation of the AMPK-Skp2-Akt axis contributes to EGF-induced glucose metabolism and cancer cell migration." (PMID 30413706, 2018). "Some common pro-inflammatory cytokines used to induce proliferation and invasion of cancer cells include lipopolysaccharide (LPS), epidermal growth factor (EGF), tumor necrosis factor α (TNFα), interleukin β (IL-β), interleukin 6 (IL-6) and prostaglandin E2 (PGE2)." (PMID 30603045, 2018). "Our studies demonstrated that high glucose in vitro might be regarded as an accelerator to increase cancer cell proliferation by enhancing the glial cell line-derived neurotrophic factor (GDNF)/RET or epidermal growth factor (EGF)/EGFR signaling pathways." (PMID 30455857, 2018). "The anti-cancer activity of this novel vaccine target the immune system, inducing an increase in the patient’s anti-Epidermal Growth Factor (EGF) antibody titers and reduction of the circulating EGF." (PMID 29661145, 2018). "EGF induces cell growth in human cancer cells and activates the Akt and ERK signaling pathways." (PMID 29212253, 2017). "In cancer, EGFR is often mutated and, for this reason, continually activated and stimulated because of the sustained production of EGFR ligands such as EGF, TGFα, amphiregulina and heparin-binding EGF." (PMID 28906427, 2017). "Treatment of cancer cells with EGF could induce the mRNA and protein levels of BCRP through MAPK/extracellular regulated kinase 1/2 (ERK1/2) signaling." (PMID 29291022, 2017). "Treatment with TQ showed significant attenuation of tumorigenic signaling, including those mediated by TGF-β, VEGF, FGF, EGF, and several other pro-mitogenic, angiogenic, and metastatic factors, with a consequent dose-dependent inhibition of cancer cell growth, migration, and invasion." (PMID 28659794, 2017). "Previous reports have shown that normal and cancer stem cells from neural and epithelial organs can be expanded as sphere-like cellular aggregates in serum-free medium containing epidermal growth factor (EGF) and basic fibroblast growth factor (bFGF)." (PMID 28076840, 2017). "The strategy of “sequestering” EGF reproduces the “hormonal castration” therapy, known to be effective in hormone-dependent tumors such as breast and prostate, thus extending this concept to other types of malignant tumors." (PMID 28348561, 2017).
cancer (continued). "The EGF-EGFR pathway plays an important role in cancer metastasis by activating the downstream PI3K/Akt, ERK and JNK pathway, the inhibition of EGFR or its downstream signal pathway will inhibit cancer metastasis, which sometimes will not reduce cell viability." (PMID 27906672, 2017). "Therefore, cancer cells of early-biopsy cultures must be weaned off of EGF and insulin prior to drug testing." (PMID 29241554, 2017). "Moreover, as EGF receptor signaling is responsible for cancer progression, this toxin can be applied in experimental cancer therapy research as a specific inhibitor of EGF signaling and cell proliferation." (PMID 28300784, 2017). "Also, miR-200c directly regulates different targets to increase cancer cell sensitivity to microtubule-disrupted chemotherapeutic drugs and inhibitors of epidermal growth factor." (PMID 28881640, 2017). "EGF-driven cell signaling contributes to unregulated progression and cancer malignancy." (PMID 28160565, 2017). "PA might inhibit the cancer by decreasing EGF, EGFR, VEGF, Fit-1 expressions, and Res could raise these effects." (PMID 28978315, 2017). "Given that EGF signaling plays an important role in cancer cell polarization and migration, we tested whether EGF may regulate PAD2 expression and activity and whether modulation of PAD2 activity may affect EGF-induced cell migration." (PMID 28549415, 2017). "In addition, the PDK1–Akt axis regulates chemotaxis of MDA-MB-231 cancer cells toward epidermal growth factor (EGF) and of T-cells; the same axis regulates neocortical neurons locomotion in developing mammalian neocortex." (PMID 28287465, 2017). "Therefore, agents or therapeutic strategies that can adequately inhibit the over activation of EGF or the downstream effectors in the signaling cascade would be interesting targets for developing as effective anti-cancer therapies." (PMID 28955234, 2017). "Furthermore, the finding that the EGF neutralizing antibody prevented the hypoxia‐induced increase in viable cell numbers supports the notion that hypoxia‐induced EGF production serves as an autocrine loop to activate EGFR in cancers." (PMID 28330951, 2017). "Importantly, inhibition of anterograde lysosome trafficking prevents EGF-mediated invasion through Matrigel in the context of transwell assays and 3D culture, highlighting the importance of lysosome trafficking in cancer invasion." (PMID 28978320, 2017). "Study has found that EGFR could be adjusted by EGF-meditated cancer cell proliferation through sialylation." (PMID 28978315, 2017). "We proposed earlier that the NTP treatment with epidermal growth factor (EGF)-conjugated gold nanoparticle (GNP) could be a new approach in targeted cancer therapy." (PMID 28887524, 2017). "We also suggest that this target-specificity of the EGF-GNP conjugates could aim cancer cells expressing high level of the EGFR such as breast cancer." (PMID 28887524, 2017). "Moreover, EGF promotes CSF-1 expression by carcinoma cells thereby generating a positive feedback loop." (PMID 28567162, 2017). "CSF-1 produced by carcinoma cells enhances the expression of EGF by macrophages." (PMID 28567162, 2017). "In addition, the proposed design enabled generation of differential microenvironments, due to the presence of two separated channels, to specifically assess the effect of distinct gradients of EGF on cancer cell invasion." (PMID 27678304, 2016). "Since cancer extracellular matrix releases EGF and HBEGF, and AREG correlated to HBEGF expression, we hypothesized that extracellular EGF and/or HBEGF induced AREG overexpression in OSCC." (PMID 27669890, 2016). "The recruitment of CAF is induced by diverse cytokines that secreted by cancer cells and other stromal cells, including transforming growth factor-β (TGFβ), epidermal growth factor (EGF), platelet-derived growth factor (PDGF) and fibroblast growth factor 2 (FGF2), CXCL12 and so on30." (PMID 27922075, 2016).
cancer (continued). "111In-labeled EGF-Au NP hold promise as a new approach to the treatment of EGFR-positive cancers." (PMID 26999580, 2016). "The first control strategy for changing the cancerous phenotype into a quiescent phenotype can be used to suppress any further progression of cancer cells into malignant types by blocking the signaling for proliferation and metastasis in response to external signals such as EGF or Wnt." (PMID 27765040, 2016). "EGF signaling plays a pivotal role in tumorigenesis, cancer progression, and metastasis." (PMID 27341132, 2016). "However, the potential physiological activation and stimulation of cancer growth has hindered the use of EGF as targeting peptide in drug delivery systems, which is dependent on the release of the anticancer drug." (PMID 27788212, 2016). "Therefore, our findings suggest that in addition to the accepted role of enhanced Wnt-β-catenin signaling in HBL, aberrant EGF-dependent cancer signaling likely contributes to HBL tumorigenesis." (PMID 27910913, 2016). "Genetic alterations of Wnt/β-catenin and EGF/Ras pathways are common in various types of cancer." (PMID 27835592, 2016). "This could be a potential area of study to investigate the prolonged spatiotemporal signaling of EGF, in relation to chemokinetic and chemotactic responses, in cancer cells." (PMID 27678304, 2016). "Hence, Mena11a reduces both cofilin-dependent (at 60 s) and Arp2/3-dependent (at 180 s) free barbed end abundance within lamellipodia of carcinoma cells stimulated with a saturating EGF concentration." (PMID 27748415, 2016). "This suggests that IGF1R may play a role in the EGF-MCSF cancer cell-TAM paracrine invasion pathway." (PMID 25629162, 2015). "In addition, recent reports suggested that EGF-mediated store-operated calcium signaling is involved to promote cancer cell invasion and metastasis in various cancers." (PMID 25797258, 2015). "In addition to this, we have also analyzed a few cancer-related pathways such as Wnt, Notch and EGF in individual KD and inhibitor treated cultures." (PMID 26081429, 2015). "To further validate the contribution of autologous sera in personalizing the explant culture, we compared the individual effects of heterologous/allogenic sera (HS) obtained from treatment naïve patients (age, sex and cancer-type matched) with AS and recombinant EGF." (PMID 25721094, 2015). "As expected, a larger number of both A549 and MCF-7 cells acquired migration and invasion ability following stimulation with TGF-β1 or EGF than the untreated control cells, suggesting that stimulation with TGF-β1 and EGF led to an enhanced migratory and invasive potential of the cancer cells." (PMID 26005723, 2015). "We then examined the influence of EGF on MMP9 transcription as well as on the transcription of additional MMPs (MMP-1, MMP-2, MMP-3, MMP-7, MMP-10, MMP-13, MMP14, MMP15) and of CD44, a cell adhesion glycoprotein implicated in EMT and cancer metastasis." (PMID 26084289, 2015). "Alternatively, evidence has shown that induction of angiogenesis by HIF-1α in cancer cells is activated by epidermal growth factor (EGF)/AKT/ERK signaling during hypoxia, and our analysis of miR-622-overexpressing cells revealed decreased HIF-1α-dependent cell invasion." (PMID 26528854, 2015). "The receptors for EGF are considered important concerning the development of cancer." (PMID 26173062, 2015). "In conclusion, the overexpression of NEU3 could cause the constitutive activation of EGFR together with Src activation in the presence of EGF, and subsequently potentiation of the tumorigenicity of cancer cells." (PMID 25803810, 2015). "Furthermore, it was shown that this interaction is mediated by a CSF-1/EGF-loop between carcinoma cells and MCs." (PMID 26098772, 2015). "Detailed follow-up experiments investigating the dynamics of endocytosis uncovered crosstalk between the cancer-related EGF and IGF pathways with so far unknown effects on endocytosis and cargo trafficking." (PMID 25188415, 2014).
cancer (continued). "A previous report showed that EGF can induce cancer cell proliferation." (PMID 25122478, 2014). "It is intriguing to note that EGF signaling is frequently deregulated in different cancers." (PMID 25493075, 2014). "The present study demonstrates that ECM1 may regulate both cancer cell proliferation and Ttzm resistance through interaction with EGF signaling." (PMID 25499743, 2014). "Taken together, our chemical genomic based pathway analysis in three cancer cell lines demonstrate consistency and variety in the EGF-induced regulatory signaling pathway for regulating cancer cell migration between cell types using a combination approach of chemical biology and systems biology." (PMID 24820097, 2014). "Importantly, these perivascular TAM produce EGF, which attracts M-CSF-producing cancer cells, resulting in a coordinated migration and intravasation of the cancer cells at sites of high macrophage density." (PMID 24723924, 2014). "Indeed, it has been shown that activation of EGF signalling in pen/lgl2 mutant leads to a cancer like phenotype in the zebrafish epidermis." (PMID 25233349, 2014). "Chemoattractants like EGF provide a directed migration for cancer cells." (PMID 24811863, 2014). "Moreover, increased level of TG2 by epidermal growth factor (EGF) treatment protects cancer cells from doxorubicin-induced apoptosis highlighting the role of TG2 in cancer cell survival." (PMID 24725450, 2014). "PTPD1, EGFR and c-SRC could then regulate actin and membrane dynamics needed to propagate EGF signals and consequently promote cancer progression." (PMID 25062045, 2014). "In addition, EGF promotes the expression of M-CSF by carcinoma cells, thereby generating a positive feedback loop." (PMID 25339957, 2014). "Indeed, since EGF signaling pathways can be deregulated at many levels during cancer progression, a multi-faceted approach to target these pathways and their regulatory mechanisms for cancer treatment is required." (PMID 23724959, 2013). "Cancer vaccine clinical trials from our own group have previously shown that age is related to the survival advantage conferred by therapeutic vaccination with an immunogenic preparation containing human Epidermal Growth Factor." (PMID 23627933, 2013). "Furthermore, EGF treatment of cancer cells leads to downregulation of Tensin3 and concomitant upregulation of cten, correlating with enhanced cell migration." (PMID 23809228, 2013). "Many studies have reported that several molecules might affect EMT of cancer cells, including TGFβ, EGF, and PDGF." (PMID 23690936, 2013). "Results obtained using reproductive and non-reproductive cells, untransformed cells (fibroblasts) or cells derived from different human cancers (prostate, breast, colon and pancreas) indicate that AR blockade by Casodex impairs EGF-elicited biological responses in these cells." (PMID 24130806, 2013). "Epidermal growth factor (EGF) is a well-known growth factor that promotes cancer progression." (PMID 23592411, 2013). "In conclusion, this study demonstrated the up-regulation of IL-1β in EGF-treated cancer cells." (PMID 23383347, 2013). "Hence, targeted therapies that block EGF signaling have been successfully applied towards anti-cancer treatment." (PMID 23724959, 2013). "Optimal exploitation of genomics and bioinformatics technologies have provided many tools that have been successfully applied to the study of EGF signaling (establishing an elaborate model of an EGF-dependent transcriptional modulator network) and to many types of cancers." (PMID 23724959, 2013). "iii) The spheroid body formation assay in which cells are cultured in non-adherent condition in a serum-free medium supplemented with basic fibroblast growth factor (bFGF) and epidermal growth factor (EGF) is a practical approach for individual solid tumor tissues or cancer cells." (PMID 23229446, 2013).
cancer (continued). "Therefore, it is conceivable that EGF/AR crosstalk plays a role in cancer development, when androgen levels decline as a consequence of ageing or pathological conditions." (PMID 24130806, 2013). "Therefore knowledge of the inhibitory mechanism related to epidermal growth factor (EGF) would assist in searching for targets in cancer therapy." (PMID 23706036, 2013). "The functional interaction analyses in this study further strengthen the importance of Ets-1 in regulating cancer metastasis due to the pathway associations we have observed in WNT, vascular endothelial growth factor, and MMP signaling, as well as ERK5, MAPK, EGF, PDGF, MET and GPCR pathways." (PMID 24280356, 2013). "Moreover, GRP78-targeting subtilase cytotoxin catalytic subunit fused with epidermal growth factor (EGF-SubA) sensitizes various cancer cells to Photofrin-mediated PDT." (PMID 23887632, 2013). "Given that there are no known naturally occurring activating mutations in the STAT3 gene, aberrant activation of STAT3 in many types of cancers is primarily due to overexpression or deregulation of upstream signaling molecules such as IL-6/gp130, EGF/EGFR, JAK2, or Src." (PMID 24260381, 2013). "The activation of EGF signaling and increase of IL-1β contributed to chemotherapeutic resistance of cancer cells, suggesting that the expression of IL-1β may be used as a biomarker to evaluate successful cancer treatment." (PMID 23383347, 2013). "EGF stimulates cancer growth through the EGFR receptor (EGFR) pathway." (PMID 23592411, 2013). "In our study, A549 cancer cell invasion induced by EGF could be observed and quantified by measuring the percentage of the cells with invadopodia and the average number of invadopodia foci per cell." (PMID 23441195, 2013). "In addition, hSpry1 overexpression suppressed the invasive capability of cancer cells to penetrate collagen layers in response to EGF, uPA, or uPA-ATF." (PMID 25937961, 2013). "To analyze signaling pathways that could mediate the effects of AZA1 mediated Rac1/Cdc42 inhibition, we examined the activity of the downstream effector PAK by evaluating PAK phosphorylation in EGF-stimulated cancer cells following AZA1 treatment." (PMID 24040362, 2013). "It has been shown that EGF promotes cancer cell proliferation, migration, and invasion." (PMID 23592411, 2013). "The members of the epidermal growth factor (EGF)/ErbB family are prime targets for cancer therapy." (PMID 23935985, 2013). "Cancer cells with EGFR overexpression showed different responsiveness to EGF." (PMID 23441195, 2013). "In this review, we first discuss the involvement of ubiquitination in the regulation of the EGF-mediated ERK signalling pathway via the EGF receptor, highlighting the interplay between ubiquitination and phosphorylation in this cancer-implicated system and addressing open questions." (PMID 23902637, 2013). "Furthermore, EGF stimulates uPAR expression and cell invasiveness in a variety of cancer cell lines." (PMID 25937961, 2013). "However, the over-expression of EGF was an aggressive biological behavior, as increased levels of EGF/EGFR were detected in innumerable types of carcinomas." (PMID 23825635, 2013). "Although EGF can elicit a variety of biological actions, including the proliferation and differentiation of epithelial and mesenchymal cells, particularly in the embryonic stage, EGFR ligands other than EGF may play crucial roles in cancer cells." (PMID 22209887, 2012). "The immunoreactivity of EGF was weak to moderate in cytoplasm of cancer cells." (PMID 23304126, 2012). "Thus, methods to identify and assess the de-regulated EGF signaling status driven by genetic/epigenetic alterations in cancer cells are necessary." (PMID 23028479, 2012). "Besides the fact that the ErbB receptors are indispensable during development and in normal adult physiology, epidermal growth factor (EGFR) and ErbB2 in particular have been implicated in the development of many human cancers." (PMID 23202898, 2012).